BRCA1 (BRCA1 DNA repair associated)
Diseases named in the same sentence as BRCA1 in open-access papers (continued):
Sharing a sentence is not in itself a finding about the gene and the disease.
cancer (continued). "In a large pan-cancer BRCA1/2 analysis, biallelic inactivation occurred in only 50% of BRCA1 mutants versus 90% of BRCA2 mutants." (PMID 39333696, 2025). "Still, there are essential dissimilarities between BRCA1 and BRCA2 with regard to their biological functions, the spectrum of associated cancer types, and the nuances of tumor presentation." (PMID 40547808, 2025). "Mutation-specific cluster regions (CR) in both genes have been identified for breast (BCCR) and ovarian (OCCR) cancer, aiding in the monitoring of patients with PVs in BRCA1 and BRCA2." (PMID 40071159, 2025). "Five women who have had RRM (all BRCA1 carriers) developed BC after RRM: the interval from RRM to the post-mastectomy cancer ranged 2.5 to 12.7 years (mean ≈ 6.5 years, median ≈ 3.0 years)." (PMID 40694193, 2025). "This function is especially crucial in BRCA1-mutated cells, where HR is already impaired, highlighting TLK as a novel regulator of PARPi activity, a promising cancer therapy that targets HR deficiencies." (PMID 39844055, 2025). "To design a rational PARPi combination therapy, we screened a library of FDA-approved drugs and identified the mutant IDH1 inhibitor ivosidenib, which greatly potentiates PARPi efficacy in either BRCA1/2 wild-type (WT) or mutant cancer cells." (PMID 40299557, 2025). "Various metrics for quantifying HRD in cancers exist, ranging from genomic scars, RAD51 foci formation, functional assays, and BRCA1/2 mutation analysis." (PMID 40842586, 2025). "Given the pivotal role of BRCA1 and the significance of variations in the vaginal microenvironment in cancer, we are keen on delving deeper into the impact of differential BRCA1 expression on the vaginal microenvironment in HGSOC." (PMID 41430564, 2025). "Loss of SETD1A from both BRCA1-deficient and ATM-deficient cancer cells was associated with resistance to Olaparib, explained by partial restoration of homologous recombination." (PMID 39994444, 2025). "Two cancer cell lines that harbor wild type BRCA1/2 and modestly respond to PARPi (OVCAR8, HGSOC; and MDA-MB-231, TNBC) were used for screening." (PMID 38826355, 2025). "Germline BRCA1 and BRCA2 testing is a standard evidence-based practice, with established risk reduction and cancer screening guidelines for genetic carriers." (PMID 40853717, 2025). "Surveillance and risk-reducing surgeries are associated with >90% reduction in cancer incidence and significantly decreased cancer mortality for female BRCA1/BRCA2 carriers." (PMID 40745491, 2025). "In other solid tumors, BRCA1/2, PALB2, or RAD51-mutated cancers have demonstrated sensitivity to platinum-based chemotherapy and PARP inhibition, supporting the rationale for evaluating similar approaches in pNENs." (PMID 41294693, 2025). "Nonetheless, many patients with BRCA1/2-mutant cancers treated with PARPi will develop resistance to treatment." (PMID 41357766, 2025). "BRCA1 and BRCA2 (BRCA1/2) are the most commonly studied genes in Caucasian cancer patients, although there are few studies on Asians." (PMID 40904409, 2025). "Eight tumours carried focal amplifications and/or deletions involving known cancer genes, as well as potential chromosomal instability-associated genes, including CCNE1 amplifications and a rare amplification of BRCA1." (PMID 40952339, 2025). "This approach was chosen due to the substantial differences in cancer risk profiles between BRCA2 and BRCA1, as well as the greater number of BRCA2 P/LP carriers in the UK Biobank, which allowed for increased statistical power." (PMID 40462315, 2025). "Cancer genome profiling tests, cancer BRCA1/2 genetic tests, and genetic counseling were accessed at 11.10% (range by prefecture: 0.0%–50.0%), 60.00% (0.0%–100.0%), and 33.30% (0.0%–72.4%) of DCCHs, respectively." (PMID 40753278, 2025). "Like those with BRCA1 mutations, people with BRCA2 mutations are more likely to develop these cancers than the general population." (PMID 40141415, 2025).
cancer (continued). "As discussed, defective BRCA1 and BRCA2 increase cancer risk in men and women due to increased genomic instability." (PMID 40429877, 2025). "We then investigated the association of six BRCA1 and BRCA2 founder mutations with the risk of DCIS using 4702 cancer-free women as a reference group." (PMID 40002208, 2025). "We found that the IDH1 inhibitor ivosidenib functions as an HR repair inhibitor by targeting YTHDC2, and a combination treatment of ivosidenib and PARPi Olaparib produced synergistic anti-tumor effects in BRCA1/2-proficient cancer cells." (PMID 40299557, 2025). "Genetic testing for germline mutations—particularly for the BRCA1 and BRCA2 genes—is a key component of hereditary cancer risk assessment and its results can influence treatment choices, preventive interventions, and family-based cascade testing." (PMID 40710012, 2025). "The aim of this study was to evaluate trends in utilization of BRCA1 and BRCA2 testing in Ontario since the inception of this program and to identify gaps in testing in order to inform targeted strategies for cancer risk reduction." (PMID 40862808, 2025). "The synthetic lethality observed between BRCA1/2 mutations and poly(ADP-ribose) polymerase (PARP) inhibition exemplifies how DDR-targeted therapies can selectively kill cancer cells with homologous recombination deficiencies while sparing normal tissues." (PMID 41373427, 2025). "Research has identified candidate genes associated with CMT development, including breast cancer gene 1 (BRCA1) and breast cancer gene 2 (BRCA2)." (PMID 40004231, 2025). "The combination of PARP inhibitors with immune checkpoint inhibitors, such as anti-PD-1 antibodies, demonstrated significant potential in treating patients with BRCA1/2-mutant cancers." (PMID 40606759, 2025). "The synthetic lethality between BRCA1/2 mutations and PARP inhibition is one of the most successful and classic precision medicine strategies in contemporary cancer therapy." (PMID 41189946, 2025). "Having pharmacologically validated the BRCA synthetic lethality, we performed a cell panel screen covering a diverse set of tumor indications to identify potential cancer subtypes with sensitivity to MSC778 beyond BRCA1/2-mediated HRD." (PMID 41359388, 2025). "Pathogenic mutations in exon 22 of BRCA1 and exon 27 of BRCA2 disrupt DNA repair mechanisms, leading to genomic instability and increased risk of cancer and progression." (PMID 40725150, 2025). "By regulating key processes such as cell cycle, DNA repair, signal transduction, and hypoxia response, these enzymes can both promote tumor development as oncogenes (e.g. MDM2) and inhibit cancer as tumor suppressor genes (e.g. BRCA1, VHL)." (PMID 40276056, 2025). "Consistently, we found, in BRCA1-expressing cancer cells, an increase in Cit at univariate statistics (×1.83)." (PMID 40863152, 2025). "BRCAness is a homologous recombination repair (HRR) deficiency phenotype mimicking BRCA1/2 loss, leading to PARP inhibitor sensitivity in BRCA-associated cancers including pancreatic cancer." (PMID 40764600, 2025). "Radiomics extracts quantitative features from MRI/CT to distinguish benign from malignant tumors; radiogenomics links imaging with BRCA1/2 status." (PMID 40940896, 2025). "For instance, while testing was initially limited to BRCA1/2 for breast and ovarian cancers, current recommendations have expanded this to include multi-gene panel testing for these and other cancer types." (PMID 41156180, 2025). "In cancer cells with homologous recombination (HR) defects—such as BRCA1/2-mutant tumours—PARP inhibition induces synthetic lethality by converting unrepaired SSBs into lethal DSBs that cannot be efficiently repaired." (PMID 40382284, 2025).
cancer (continued). "To examine whether UCP1-CRISPRa mammary adipocytes might prevent cancer development in individuals at high lifetime risk of cancer, we co-cultured them alongside breast organoids from dissected patient-matched breast tissue of BRCA1/BRCA2/RAD51D mutation carriers." (PMID 39905264, 2025). "This lethality is a possible explanation because the cancer cells with defects in the BRCA1/2 gene are defective in HR repair." (PMID 41155174, 2025). "In the current Cancer Research UK-funded study called Precision HBOC, a SNP313 PRS is being used to stratify risk in BRCA1 and BRCA2 carriers." (PMID 40227593, 2025). "Numerous studies have elucidated the pivotal roles of ATM and BRCA1/2 genes in cancer progression, therapeutic resistance, and immune modulation, highlighting their potential as therapeutic targets across diverse malignancies." (PMID 40256842, 2025). "We found a double mutation (DM) in 6 patients, with one carrying a DM in MUTYH and the other 5 harboring mutations in MUTYH and other cancer susceptibility genes (CHEK2, BRIP1, MLH1, and BRCA1)." (PMID 41001951, 2025). "Three of these four genes, BRCA1, PSMD4, and RPL3, are reported as cancer genes, and STAT1 is associated with both cancer and AIDs." (PMID 40429780, 2025). "DNMT1 is a critical enzyme responsible for maintaining DNA methylation patterns and regulating gene expression, particularly in tumor suppressor genes (TSGs) such as p16INK4 and BRCA1, frequently silenced in cancer." (PMID 39996888, 2025). "Meanwhile, the percentages of patients with the BRCA1/2 genetic test fee, genetic counseling, and cancer genome profiling test fees were 60.00%, 33.00%, and 11.10%, respectively." (PMID 40753278, 2025). "The function of BRCA1 in controlling the cell cycle and apoptosis highlights how important it is for preserving cellular integrity and halting the growth of cancer." (PMID 40141415, 2025). "Germline testing was performed using a 25-gene hereditary cancer panel and by BRCA1/2 next-generation sequencing." (PMID 41156180, 2025). "BRCA1-associated cancers exhibited higher nuclear and histological grades compared to BRCA2-associated cancers." (PMID 41083355, 2025). "Ultimately, this work provides insight into the broad selectivity of MX that underlies its general cytotoxicity and exposes an additional vulnerability in BRCA1− UWB1.289 cancer cells." (PMID 41283651, 2025). "BRCA1 and BRCA2 are among the most studied cancer susceptibility genes, significantly increasing the risk of breast, ovarian, pancreatic and prostate cancers." (PMID 40943312, 2025). "Thirdly, these mutations do not significantly influence the immune microenvironment, except in ovarian BRCA1-mutant cancers where the upregulation of chemokines and antigen-presenting cell components is observed." (PMID 40647506, 2025). "Ever since the specific killing of BRCA1‐ or BRCA2‐deficient tumor cells by PARP inhibition was reported, several PARP inhibitors have been successfully developed and used for cancer therapy." (PMID 39462683, 2025). "The role of BRCA1 in regulating NRF2 activity has implications for the etiology and treatment of BRCA1-related cancers." (PMID 41333220, 2025). "Notably, TLK2 expression did not exhibit the same correlation with the DepMap score, suggesting that TLK1 and TLK2 may have differential effects on cellular sensitivity to PARP disruption in the context of BRCA1 deficiency, and that these effects may be cancer type- and context-dependent." (PMID 39844055, 2025). "BRCA1/2 gene mutations, prevalent in younger BC patients, impair cardioprotective effects, elevating CVD risk alongside cancer treatments." (PMID 39838506, 2025).
cancer (continued). "The value of the present study lies in its findings being consistent with previous literature, yet offering a unique perspective on the personal experience of BRCA1/2 carriers who underwent cancer genetic counselling." (PMID 40596937, 2025). "Family history was also important as probands with a family history of BRCA1/2 related cancers were found to be more than twice as likely to proceed with testing." (PMID 40042150, 2025). "The MRI screening process significantly increases the early detection of cancer among BRCA1/2 carriers." (PMID 41150754, 2025). "This review aims to expand the discussion of BRCA1 and BRCA2 beyond their association with CMTs, exploring their broader implications in the oncogenesis of various dog cancers." (PMID 40004231, 2025). "Pedigrees of BRCA1/2 and PALB2 variant carrier cases indicated that breast and other cancer types are often accumulated in these families, providing further evidence for the presence of inherited risk factors." (PMID 40009290, 2025). "In cancer cells with defective BRCA1/2 or other defects in homologous recombination repair (HRR), DNA replication results in irreversible double-strand breaks." (PMID 40141415, 2025). "In such a scenario, it would be predicted that BRCA-proficient cancer cells need to enhance the activation of homologous recombination factors such as BRCA1, BRCA2, and RAD51 to repair dsDNA breaks." (PMID 40243501, 2025). "Methylstat modulated clonal cancer dynamics by mitigating positive selection of PARPi-resistant or BRCA1-proficient cells under olaparib treatment." (PMID 39915607, 2025). "This revealed that BRCA1- and ATM-deficient cancer patients with low SETD1A mRNA expression had poorer overall survival outcomes compared to those with higher levels of SETD1A." (PMID 39994444, 2025). "We assumed that BRCA1 carriers with unfavorable genomic context are likely to develop cancer disease at an earlier age when compared to women with disease-protective allele combinations." (PMID 41374957, 2025). "Relatives, i.e. healthy individuals or cancer patients who underwent cascade genetic testing due to the previous identification of a BRCA1/2 PV in their family." (PMID 40596937, 2025). "Variants in HR genes, such as BRCA1 and BRCA2 are known to increase cancer risk, particularly for breast and ovarian cancers." (PMID 40047910, 2025). "Approximately 10% of patients with aggressive PC carry germline pathogenic variants in genes with established roles in cancer predisposition (BRCA2, ATM, CHEK2, NBN, BRCA1, PALB2, BRIP1, BARD1)." (PMID 41465280, 2025). "Cdk1 inhibition has been reported to sensitize BRCA-proficient cancers to PARP inhibition by impairing BRCA1 function." (PMID 40764600, 2025). "Among other cancer susceptibility genes, associations were seen for ATM (p = 0.0013), BRCA1 (p = 0.0015), BARD1 (p = 0.00021), CHEK2 (p = 0.039), RAD51D (p = 0.0065), MSH3 (p = 0.0025)." (PMID 39749474, 2025). "To study the cancer development in these patients, we established a protocol for the generation of human ER/PR/HER2-negative breast organoids carrying a BRCA1 germline mutation." (PMID 41283387, 2025). "This accumulation, along with the interaction between EWS-FLI1 and BRCA1, hinders homologous recombination and contributes to genomic instability in cancer cells." (PMID 40271193, 2025). "A younger median of cancer was similarly reported in Koreans by Bang, Kwon (33.7 years) and Hur, Kim (36 years) when compared to single BRCA1/BRCA2 carriers." (PMID 39843919, 2025).
cancer (continued). "Given improved prevention and survival, knowledge regarding possible increased risks for other types of cancer at an early age in BRCA1/2 GPV carriers is becoming increasingly relevant." (PMID 40427184, 2025). "It is through HRD that BRCA1 and BRCA2 carriers are thought to be at an increased risk for various cancers." (PMID 41256354, 2025). "Based on this analysis, the genes STAT3, MYC, CTNNB1, ESR1, JUN, and BRCA1 emerged as pivotal genes, indicating their significant impact on each cancer type in response to radiation exposure." (PMID 41186627, 2025). "Analysis of breast and leukocyte DNA in over 400 TNBC patients showed that 20% of cancers originated from normal cells with BRCA1 epigenetic alterations." (PMID 41049008, 2025). "This large proportion of potentially preventable cancers further supports BRCA1/BRCA2 screening before age 40 years in populations with high carrier rates." (PMID 40116830, 2025). "Biomarkers in BC often focus on obvious genes in line with hallmarks of cancer that contribute to malignant tumor growth, particularly oncogenes and tumor suppressor genes (i.e. BRCA1 and BRCA2)." (PMID 39838298, 2025). "In contrast, BRCA1/2−/− tumors represented a substantially smaller fraction (21.9%) of HRD cases in other cancer types." (PMID 41279139, 2025). "Variants in BRCA1 and BRCA2 disrupt the HRR pathway, compromising the ability of cancer cells to repair platinum-induced DNA damage and thereby increasing their sensitivity to platinum-based chemotherapy." (PMID 40777133, 2025). "It has been reported that HRD is ubiquitous in a variety of cancers, and ATM and BRCA1/2 have been found to be important mutation drivers." (PMID 39931080, 2025). "For example, restoration of homologous recombination by backmutation in BRCA1/2-mutant cancers abrogates sensitivity to cisplatin and other DNA crosslinking agents." (PMID 41373545, 2025). "This study compared the frequency of presumed germline BRCA1/2 variants identified by CGP testing in the regional area of Japan with that in the regional healthy and/or nationwide cancer cohorts." (PMID 40249378, 2025). "In the current study, we determined the GIS in association with the mutational status of BRCA1, BRCA2, and 20 other HRR‐related genes across 143 tumors from 24 cancer entities with HRR pathway alterations." (PMID 40278800, 2025). "Of these, 103 patients (8.6% of the total sample) carried germline pathogenic variants in genes that have been definitively linked to an increased risk of PC or other types of cancers (BRCA2, ATM, CHEK2, NBN, BRCA1, PALB2, BRIP1 and BARD1)." (PMID 41465280, 2025). "In this study, we demonstrated that FAM111B expression correlates with 17 HR repair proteins, including ATM, ATR, and BRCA1/2, in 30 out of 33 of the studied cancers." (PMID 40243892, 2025). "The remaining eight participants had their P/LP variants validated at the HMC laboratory (five GPPs in BRCA1 and three GPPs in BRCA2) and were referred to the cancer genetics and high-risk surveillance program." (PMID 41463058, 2025). "One of the first mechanisms of resistance identified is up-regulation of the multidrug resistance 1 (MDR1) transporter, initially reported in a genetically engineered BRCA1 mouse model and later in tissues from PARPi-treated cancers." (PMID 39927794, 2025). "Here, we uncover the defect in the RNA editing enzyme ADAR1 as a novel genetic vulnerability of BRCA1/2-mutant (BRCAm) cancer cells." (PMID 40730818, 2025).